KLF3 (KLF transcription factor 3)
Diseases named in the same sentence as KLF3 in open-access papers (continued):
Sharing a sentence is not in itself a finding about the gene and the disease.
aortic valvular stenosis (1 paper, 2013). "In a screen for dominant mutations affecting cardiovascular function in N-ethyl-N-nitrosourea (ENU) mutagenized mice, we identified a missense mutation in the Klf3 gene that caused aortic valvular stenosis and partially penetrant perinatal lethality in heterozygotes." (PMID 23874215, 2013). "Thus local alterations in KLF3 transcriptional activity in cardiovascular cells may directly cause aortic valvular stenosis, hypotension, and abnormal myocardial growth." (PMID 23874215, 2013). "In adults, high cardiac output and cardiac hypertrophy due to chamber enlargement (i.e. eccentric growth) with no change in left ventricular wall thickness was paradoxical given aortic valvular stenosis in adult Klf3 point mutant and gene trap mutants." (PMID 23874215, 2013).
brain tumors (1 paper, 2023). "KLF6 expression is elevated in ovarian malignancies, KLF8 promotes cellular proliferation in HCC, gastric, and glioma carcinomas, while KLF3 and KLF14 have been reported to inhibit tumor growth in breast and brain tumors, respectively." (PMID 37833790, 2023).
congenital heart disease (1 paper, 2019). A heart disease that is present at birth. "Interestingly, there is also a dominant mutation in murine Klf3 at the + 3 position in ZF1 (H275R) which was discovered in an ENU-generated mouse with congenital heart disease (CHD)." (PMID 31126231, 2019).
Diabetes (1 paper, 2022). "Diabetes is also associated with upregulation of vascular inflammation including the induction of pro-atherogenic mediators in the thoracic aorta, including the adhesion molecule (VCAM-1) and inflammatory markers (TNFα, IL-6, MCP-1, CD11b, and KLF3)." (PMID 35624851, 2022).
esophageal squamous cell carcinoma (1 paper, 2022). Esophageal squamous cell carcinoma (ESCC) is a type of esophageal carcinoma (EC) that can affect any part of the esophagus, but is usually located in the upper or middle third. "Besides, a decrease is manifested in KLF3 expression in esophageal squamous cell carcinoma and further depletion of KLF3 augments the migration and invasion of cancer cells." (PMID 33728488, 2022).
lung disease (1 paper, 2022). "The causal chain means that the KLF3 gene may inhibit lung disease." (PMID 36299590, 2022).
myeloid leukemia (1 paper, 2022). A clonal proliferation of myeloid cells and their precursors in the bone marrow, peripheral blood, and spleen. "Interestingly, previous evidence shows that HBG1, KLF1, and KLF3 are up-regulated in the β globin knockout human erythroid progenitor cell model, relative to controls and in human myeloid leukemia cells." (PMID 35627314, 2022).
myeloproliferative disorder (1 paper, 2013). A clonal hematopoietic stem cell disorder, characterized by proliferation in the bone marrow of one or more of the myeloid (i.e., granulocytic, erythroid, megakaryocytic, and mast cell) lineages. "KLFs 4, 5 and 10 are important in T-cell activation and trafficking and KLF4 may function as a tumor suppressor in adult T-cell leukemia, KLF2 promotes memory B-cell differentiation and KLF3-deficient mice display a myeloproliferative disorder." (PMID 24130502, 2013).
ovarian carcinoma (1 paper, 2020). A malignant neoplasm originating from the surface ovarian epithelium. "Similarly, lower KLF3 and miR-124 expression was indicated in aggressiveness and metastatic uterine and cervical and ovarian cancers." (PMID 33490232, 2020).
rectal cancer (1 paper, 2022). A primary or metastatic malignant neoplasm that affects the rectum. "KLF3 and KLF6 expressions were favourably related to the infiltration levels of all immune cell types except CD4+ T cells in rectal cancer." (PMID 35345512, 2022).
schizophrenia (1 paper, 2025). A major psychotic disorder characterized by abnormalities in the perception or expression of reality. "Furthermore, we identified six genes—GRK2, KLF3, TAOK2, ARFGAP45, AP1M1, and GPAT2—that were shared across gene sets associated with both brain function and clinical symptoms, suggesting a common transcriptional basis for these features of schizophrenia." (PMID 41271614, 2025). "An intersection analysis revealed six genes-GRK2, KLF3, TAOK2, ARFGAP45, AP1M1, and GPAT2-common to both brain function and clinical symptomatology gene sets, highlighting a shared genetic etiology in schizophrenia’s neuroimaging and clinical manifestations." (PMID 41271614, 2025).
tumor (28 papers, 2006 to 2025). "Correlation analysis was used to explore the relationship between KLF3 expression and tumor mutation burden, microsatellite instability, and immune-related genes." (PMID 37600783, 2023). "Xenograft assay was then performed with KLF3-deficient HCT116, and the result indicated that KLF3 knockdown repressed tumor growth in mice." (PMID 34737287, 2021). "Downregulated KLF3 was associated with accelerated tumor growth in vivo." (PMID 38305787, 2024). "Summary of methylation sites most negatively associated with KLF3 gene expression by tumor type." (PMID 37600783, 2023). "We also evaluated the association between DNA methylation and mRNA expression of KLFs in PCa tumour tissues and found that the mRNA expression of most KLFs was negatively associated with its DNA methylation at the promoter region (P < .05), except for KLF3, KLF9 and KLF17." (PMID 32281273, 2020). "The suppression of KLF3 expression greatly increased tumor volume (p< 0.05) and weight in a time-conditioned manner (p< 0.05)." (PMID 38305787, 2024). "The expression of Ki67, a proliferation marker, was examined in tumor specimens to assess the impact of sh-KLF3#1 on proliferation." (PMID 38305787, 2024). "The tumor-promoting capacity of KLF3 was explored by performing in vitro functional experiments using CRC cells." (PMID 38305787, 2024). "Tissue samples (n=8) along with paired tumor-adjacent normal tissues were assessed through qRT-PCR and western blotting to analyze KLF3 expression." (PMID 38305787, 2024). "The effects of KLF3 on tumor development were examined by subcutaneously injecting BALB/c nude mice with HCT116 cells containing sh-KLF3#1." (PMID 38305787, 2024). "Further, in vivo experiments revealed that tumor growth was significantly slower in PANC-1 cells with stably silenced KLF3 expression compared to the control group (p<0.01)." (PMID 37600783, 2023). "Functional analysis and gene set enrichment analysis found that KLF3 was involved in various immune-related pathways and tumor progression-related pathways." (PMID 37600783, 2023). "The role of KLF3 in the tumor microenvironment of various types of tumors cannot be underestimated, and it has significant potential as a biomarker for predicting the response to immunotherapy." (PMID 37600783, 2023). "Further, we established a COX proportional regression model on the pan-cancer patient survival data and KLF3 expression to analyze the relationship between KLF3 gene expression and prognosis in each tumor." (PMID 37600783, 2023). "The GSCA database provided the methylation sites most negatively correlated with KLF3 gene expression in each tumor type." (PMID 37600783, 2023). "In order to investigate the expression differences of KLF3 in tumor and normal tissues in pan-cancer, we conducted the following analysis." (PMID 37600783, 2023). "The role of KLF3 in the tumor immune microenvironment was further analyzed, and the relationship between KLF3 and immunotherapy response and related sensitive drugs was evaluated." (PMID 37600783, 2023). "The relationship between KLF3 expression and tumor immune microenvironment was calculated by ESTIMATE, EPIC, and MCPCOUNTER algorithms." (PMID 37600783, 2023). "TISCH and CancerSEA databases analyzed the expression distribution and function of KLF3 in the tumor microenvironment." (PMID 37600783, 2023). "Our study also found that KLF3 mRNA was significantly upregulated in 14 tumor types and significantly downregulated in 13 tumor types compared to normal tissue." (PMID 37600783, 2023). "Further, we predicted the response and sensitivity of tumor patients to immunotherapy drugs based on KLF3 expression." (PMID 37600783, 2023). "KLF3 regulates tumor cell proliferation, apoptosis, and metastasis and involves modifying the protein that has been discovered in many malignancies." (PMID 35345512, 2022).
tumor (continued). "Further experiments revealed that miR-365a-3p suppressed the migration, invasion and chemoresistance of tumor cells by inhibiting KLF3." (PMID 34539888, 2021). "This suggests that the lower expression of KLF3 and miR-124 and enhanced expression of TPD52 have association with tumor metastatic potential and stage progression." (PMID 33490232, 2020). "KLF3 acts as an oncogene in cervical and lung tumors while in acute myeloid leukemia and pancreatic and prostate cancer, it displays tumor-suppressive behavior." (PMID 33490232, 2020). "Subsequently, the expression levels of circ_0084043, miR-31, and KLF3 in the removed tumor tissues were examined." (PMID 33817265, 2020). "We found that the expression of TPD52 is higher in advanced-stage and metastatic breast cancer while the expression of KLF3 and miR-124 is lower in advanced clinical stages of tumor in comparison to initial stages." (PMID 33490232, 2020). "We performed a series of experiments and analysis, including RT-qPCR, western blots, CCK-8 assay, and migration/invasion assay, to investigate the expressions of NEAT1, miR-23a-5p and KLF3, cell viabilities, and tumor growth in vivo." (PMID 31462890, 2019). "Together, these results suggest that KLF3 is involved in the tumour growth of A549 and 95D cells through regulating JAK2/STAT3 and PI3K/AKT signalling pathways in vivo." (PMID 30485570, 2019). "Based on the current observations, we propose that KLF3 expression may correlate with tumor outcomes." (PMID 38305787, 2024). "-Modulates KLF3 in HCC tumour cells, therefore inducing HCC progression." (PMID 37894344, 2023). "Moreover, miR-660-5p secreted from M2 macrophages modulates Kruppel-like factor 3 (KLF3) in HCC tumour cells, therefore inducing HCC progression." (PMID 37894344, 2023). "In this study, KLF3 was aberrantly expressed in a variety of tumor types and was strongly correlated with clinical progression and prognosis; KLF3 could be a potential prognostic marker, especially in PAAD." (PMID 37600783, 2023). "All these support the potential tumor-suppressor role of KLF3." (PMID 35311620, 2022). "KLF3 the target gene of miR-21 is suggested to be an anti-tumor actor in tumors." (PMID 33728488, 2022). "In this study, we detected the expressions of Krüppel-like factor 3 (KLF3) in OS cells and tissues and found that the mRNA and protein levels of KLF3 were increased in OS cells and tissues and significantly related to tumor size, metastasis, and TNM stage and poor prognosis of OS patients." (PMID 35311620, 2022). "Studies in other tumor types have reported KLF3 alterations as adverse prognosticators." (PMID 35081118, 2022). "For example, tumor-promoting miRNA-27a-3p and miRNA-660-5p loaded in M2-sEVs lead to the overexpression of these in HCC cells, respectively, downregulating thioredoxin-interacting protein (TXNIP) and Krüppel-like factor 3 (KLF3) that can inhibit tumor development." (PMID 35832790, 2022). "Moreover, circ_0084043 knockdown impeded tumor growth in vivo and suppressed the level of Glut1 by modulating miR-31 and KLF3." (PMID 33817265, 2020). "The distinct splicing, differential enrichment of KLF3 and leading pathways in diverse organs may result in contrasting level of KLF3 in the development of tumours." (PMID 30485570, 2019). "This study found that the expression of KLF3 was roughly positively correlated with the expression of genes related to M2 macrophages and CAFs, which may suggest that the high expression of KLF3 can promote the formation of a microenvironment suitable for tumor cell growth." (PMID 37600783, 2023). "KLF3 expression was negatively correlated with the cell cycle, DNA damage cancer injury, DNA repair, and invasive ability of most tumors, while positively correlated with tumor differentiation, EMT, hypoxia, inflammation, metastasis, proliferation, quiescence, and stemness." (PMID 37600783, 2023). "These suggest that KLF3 may be a potential tumor suppressor gene." (PMID 35311620, 2022).
tumor (continued). "In addition, the downregulation of KLF3 suppressed tumour growth in vivo." (PMID 30485570, 2019). "Summary of correlations between KLF3 mRNA expression and gene copy number variation (CNV) across tumor types." (PMID 37600783, 2023). "However, the role of KLF3 in the pan-cancer and tumor microenvironment remains unclear." (PMID 37600783, 2023). "A similar analysis based on KLF3 and PDK2 expression, separated two major tumor groups, for which patients in the group with high PDK2 and low KLF3 expression had the lowest survival probability." (PMID 17054779, 2006). "One group was associated with rapid proliferation, oxidative phosphorylation, invasiveness, and tumor size (MRPS23, MRPL11, CKS2, LSM3, TBX3, MSN) and another with hypoxia tolerance, anaerobic metabolism, and high lactate content (PDK2, KLF3)." (PMID 17054779, 2006). "Higher KLF3 levels in CRC could activate cancer-inhibitory pathways, whereas its lower levels activated cancer-promoting pathways, accelerating tumor progression." (PMID 38305787, 2024). "In addition, based on single-cell sequencing analysis, it was found that KLF3 was mainly expressed in CD4Tconv, CD8T, monocytes/macrophages, endothelial cells, and malignant cells in most of the tumor microenvironment." (PMID 37600783, 2023). "We did not observe a significant difference between the adjacent and cancer tissues in our collection; among TCGA samples, KLF3 expression was higher in tumor tissues but not significant enough." (PMID 34737287, 2021). "However, the relationship between KLF3 and pan-cancer TME and tumor immune cell infiltration remains largely unknown." (PMID 37600783, 2023). "Here, our stage-specific analysis of TCGA mutation data for non-ultramutated EECs showed that KLF3 and PAX6 are SMGs in late-stage (III/IV) but not early-stage (I/II) disease, raising the possibility that KLF3 and PAX6 mutations undergo positive selection during tumor progression." (PMID 35081118, 2022). "Here we propose that NK-like cells expressed the transcription factors KLF2, KLF3, and MYBL1, which have been also reported as features of cytotoxic, non-dysfunctional subsets in tumours infiltrating T cells." (PMID 38012187, 2023).
cancer (20 papers, 2014 to 2025). A tumor composed of atypical neoplastic, often pleomorphic cells that invade other tissues. "In pan-cancer, the frequency of KLF3 gene mutations in “deep deletion”, “structural variation” and “multiple Alterations” was generally less than 0.5%." (PMID 37600783, 2023). "While the involvement of KLF3 in the development of the hematopoietic system has been extensively studied, its role in cancer remains relatively yet to be elucidated." (PMID 38305787, 2024). "For example, M2-Exos transmit miR-27a-3p and miR-660-5p to HCC cells, enhancing their proliferation, migration, and invasion by downregulating TXNIP and Krüppel-like factor 3 (KLF3), respectively, while inducing cancer stemness." (PMID 39896803, 2024). "In this study, a systematic analysis of KLF3 expression profile, genetic alteration, DNA methylation, RNA modification, clinical significance, and prognostic value in pan-cancer was performed." (PMID 37600783, 2023). "Through our analysis of KLF3 in pan-cancer, we found that KLF3 is significantly upregulated in PAAD and its expression positively correlates with patient clinical stage and histological grade." (PMID 37600783, 2023). "From a pan-cancer perspective, KLF3 was generally positively correlated with the expression of markers associated with M2 macrophages and CAFs." (PMID 37600783, 2023). "TCGA and GTEx databases were used to evaluate the expression difference of KLF3 in pan-cancer and normal tissues." (PMID 37600783, 2023). "We found that KLF3 expression was generally positively correlated with m1A, m5C, and m6A-related gene expression in pan-cancer, especially in YTHDF1, NSUN3, TET2, METTL14, YTHDC2, and FMR1." (PMID 37600783, 2023). "In this study, KLF3 expression was correlated with pan-cancer TMB, MSI, immune activation/inhibition-related genes, T-cell exhaustion, M2 macrophages and CAFs-related genes, and TME." (PMID 37600783, 2023). "In this study, a comprehensive bioinformatics analysis of KLF3 was conducted through multiple databases to clarify the expression, abnormal variation, and clinical significance of KLF3 in pan-cancer." (PMID 37600783, 2023). "In cancer cells, miR-21 downregulates the expression of transcription factor KLF3 to promote NANOG/OCT4-dependent cancer cell stemness program." (PMID 34591242, 2021). "In fact, TCF25, has been involved in embryonic development expressed in brain, and KLF3, has been reported to show rearrangements in different cancer types." (PMID 24884915, 2014). "Recent studies have uncovered multiple functions of KLF3 in several types of cancers." (PMID 38305787, 2024). "For deeper insights into the impact of KLF3 on cancer, we examined how KLF3 influences the proliferation, motility, and invasiveness of the cells and unveiled that reduced KLF3 expression facilitated the manifestation of these malignant characteristics in CRC cells." (PMID 38305787, 2024). "However, the expression levels and clinical significance of KLF3 in most cancer types remain to be elucidated." (PMID 37600783, 2023). "In summary, KLF3 can effectively predict the prognosis of many cancers and is most evident in PAAD." (PMID 37600783, 2023). "KLF3 acts as a tumor suppressor gene in cancers and suppresses stemness-related genes." (PMID 33728488, 2022). "Furthermore, abnormally expressed miRNAs have been reported within various cancers, for instance, miR-185-5p serves as a tumor-promoting gene, and KLF3 plays critical biological impacts on cancer apoptosis." (PMID 35619921, 2022). "Interestingly, KLF3 is lower expressed in the cancer tissues of the CMS1 group, and higher expressed in the CMS3 group." (PMID 34737287, 2021). "Interestingly, the role of KLF3 varied in different types of cancers." (PMID 33817265, 2020). "This might be due to the different expression patterns of KLF3 in different cancers." (PMID 33817265, 2020). "However, in other cancers, KLF3 and KLF15 might have carcinogenic properties." (PMID 41155227, 2025).
cancer (continued). "For example de novo motif analysis revealed enrichment of potential cooperative factors that exert known roles in cancer progression (e.g., HIC2, KLF3, SOX2); the relative impact of these likely contributing factors should be assessed." (PMID 34773073, 2022). "Then we analyzed the relationship between KLF3 expression and TME in pan-cancer." (PMID 37600783, 2023). "Through a literature review, it is also revealed that KLF3, TPD52, PKCε, and miR-124 interact with different downstream signaling molecules of these pathways in different cancers and lead to cancer proliferation, stage progression and metastasis, and drug resistance." (PMID 33490232, 2020). "KLF3 could inhibit cellular growth and suppress transformation mediated by oncogenic KRAS (V-Ki-ras2 Kirsten rat sarcoma viral oncogene homologue) and increase apoptosis in cancer cells (Fernandez-zapico, Lomberk & Tsuji, 2011)." (PMID 31293827, 2019). "However, the potential role of KLF3 in cancers is not clear and needs to be explored." (PMID 33817265, 2020).
brain disorder (1 paper, 2025). A disease affecting the brain or part of the brain. "Finally, two BAG-associated hub transcription factor genes, KLF3 and SOX10, were identified as regulators of pleiotropic risk genes for diverse brain disorders." (PMID 40795387, 2025).